CRP (C-reactive protein)
Diseases named in the same sentence as CRP in open-access papers (continued):
Sharing a sentence is not in itself a finding about the gene and the disease.
respiratory failure (continued). "Bronchiectasis patients with respiratory failure exhibited significantly higher levels of white blood cell count as well as C-reactive protein." (PMID 36851751, 2023). "The median time to the onset of respiratory failure was 8 days in both the high CRP group and ICI within 90 days group, similar to that in a previous report." (PMID 36316726, 2022). "PedSep-B is characterized by multiple organ failure requiring intubation for more severe respiratory failure, shock, and central nervous system dysfunction with increased C-reactive protein levels and 12% mortality." (PMID 35526000, 2022). "In the analyses with all statistically significant variables in the univariate logistic regression, severe pulmonary involvement, high CRP, low hemoglobin, and vitamin D predicted respiratory failure with the need for mechanical ventilation." (PMID 35172759, 2022). "IL-6 and its downstream target CRP reflect cytokine storm in the critical stage, thus, serving as useful indicators of respiratory failure and inferior prognosis." (PMID 36438922, 2022). "The high CRP (≥ 2.75 mg/dL) group had a significantly shorter time to respiratory failure than the low CRP (< 2.75 mg/dL) group (p = 0.004)." (PMID 36316726, 2022). "Other studies demonstrated that elevated IL-6 concomitantly with raised CRP were highly expected to indicate respiratory failure." (PMID 35530861, 2022). "Severe pulmonary involvement and higher levels of CRP, IL-6, D-dimer, AST, creatinine, myoglobin, and lower levels of Tlymp, Hb, and 25(OH)D were associated with respiratory failure." (PMID 35172759, 2022). "CRP has also been used as a therapeutic target in a small number of patients with respiratory failure and severe pulmonary infiltrates." (PMID 35888173, 2022). "The median time to onset of respiratory failure in the high CRP and ICI groups were 8 (range, 1 − 10) and 8 (range, 1 − 10) days, respectively." (PMID 36316726, 2022). "Levels of D-dimers, activated partial thromboplastin time (aPTT), C-reactive protein (CRP), and interleukin (IL)-6 were significantly higher in patients with severe compared with moderate respiratory failure." (PMID 34638691, 2021). "CRP and IL-6 concentrations were significantly higher in the blood of patients with severe respiratory failure compared to patients with moderate respiratory failure, while in this group the highest values were found at acute onset." (PMID 34638691, 2021). "Our study revealed the high correlation coefficients of the serum level of IL-6 and CRP to minimum SpO2/FiO2 ratio, demonstrating that increase of the two markers indicates respiratory failure within three days after laboratory measurement." (PMID 34441262, 2021). "Results showed that performance status and hemoglobin and albumin levels, but not ESMcsa/BSA and BMI, were significantly associated with in-hospital mortality after adjusting for age, comorbidities, CRP level, and respiratory failure." (PMID 33849637, 2021). "Further, first patients suffering from Covid-19 have been treated with CRP apheresis in order to inhibit the CRP-mediated autoimmune response leading to respiratory failure and multi-organ failure." (PMID 32932587, 2020). "Cytokine release syndrome, a state characterized by worsening respiratory failure and markedly elevated inflammatory markers such as CRP, LDH, and ferritin, is a frequent consequence of COVID-19 infection, similar to SARS and MERS-CoV." (PMID 32835113, 2020). "In a study involving patients with diseases that result in respiratory failure, patients with bronchiectasis were shown to have higher CRP levels compared to the other patient groups, and CRP levels were associated with mortality in that study." (PMID 29270068, 2017). "BNP and CRP data from 147 patients who presented to the emergency department due to acute respiratory failure with bilateral pulmonary infiltrates were analyzed." (PMID 21696613, 2011).
respiratory failure (continued). "We therefore assessed the diagnostic utility of measuring the plasma BNP levels combined with CRP levels in patients with hypoxic acute respiratory failure due to CPE versus ALI/ARDS." (PMID 21696613, 2011). "Significant predictors of respiratory failure in children with MPP included CRP (OR ═ 1.013, 95% CI ═ 1.002–1.025), IL-10 (OR ═ 1.034, 95% CI ═ 1.002–1.068), APTT (OR ═ 1.095, 95% CI ═ 1.009–1.187), D-dimer (OR ═ 1.287, 95% CI ═ 1.081–1.532), and HB (OR ═ 0.972, 95% CI ═ 0.941–0.998) (P < 0.05)." (PMID 39849991, 2025). "Factors independently associated with the development of respiratory failure include the high degree of hypoxemia, a high percentage of neutrophils in the bronchoalveolar lavage fluid (BALF) cell count, and high C-reactive protein (CRP) levels." (PMID 39257888, 2024). "Significant predictors of early-postoperative mortality were female sex, increasing age, higher ASA grade, perioperative hypotension, reduced GCS, urgency of surgery and signs of cardiac or respiratory failure and frailty, increasing blood lactate and CRP levels." (PMID 36609892, 2023). "The C-reactive protein-to-albumin ratio (CAR) was recognized in a recent study as a marker of respiratory failure in Guillain Barre syndrome, with CAR>0.21 having a positive correlation and CAR>0.19, coinciding with an increased risk of aggressive disease with a low prospect of recuperation." (PMID 39554800, 2023). "Finally, we assessed the link between CRP, neutrophils, and lymphocytes with P/F ratio to better understand the individual role of mediators leading to respiratory failure." (PMID 37373750, 2023). "Low serum Mg at admission significantly predicted in-hospital death (HR = 1.29; 95% CI: 1.03–2.68) after adjusting for age, sex, comorbidities, renal function, presence of respiratory failure, CRP, hemoglobin, and maximum Mg serum levels during hospitalization." (PMID 36839188, 2023). "Some studies have also evaluated CRP trajectories during hospitalisation, showing that rapidly rising CRP levels may predict respiratory failure and that CRP peak is higher in patients who require intubation or die12–18." (PMID 35277562, 2022). "Since a CRP level above the cutoff value and history of ICI administration within 90 days were significantly associated with respiratory failure in the univariate analysis, we examined the effect of high CRP level and history of ICI administration within 90 days on the time to respiratory failure." (PMID 36316726, 2022). "If both high CRP level and a history of ICI administration within 90 days were considered risk factors, then there were four patients with both risk factors, all of whom developed respiratory failure." (PMID 36316726, 2022). "Although the time to onset of respiratory failure was significantly faster in the high CRP group and ICI within 90 days group, it should be noted that the results may be biased due to the small number of cases in this study." (PMID 36316726, 2022). "-Decreased the duration of mechanical ventilation-Lowered the risk of respiratory failure and death-Chest CT improvement-Lowered the need for ventilator, decreased the severe biomarkers (LDH, CRP and D dimer)-Decrease in time of hospitalization and significant reduction in mortality rate." (PMID 36295089, 2022). "COVID-19 disease is mainly characterized by symptoms such as fever, weakness, muscle pain, cough, headache, and high levels of CRP and inflammatory cytokines, with severe symptoms involving multiple organs; respiratory failure, acute cardiac, and kidney injuries result in patients' death eventually." (PMID 35958125, 2022). "First, transplant patients with severe COVID-19 disease (characterized by either death or prolonged course with respiratory failure requiring intubation) had the same elevated inflammatory markers (IL-6, CRP, ESR, fibrinogen, D-dimer, ferritin, and LDH) observed in non-transplant patients." (PMID 36591281, 2022).
respiratory failure (continued). "Moreover, a study demonstrated that IL-6 and CRP in combination can predict the development of respiratory failure with substantial sensitivity and specificity." (PMID 35806986, 2022). "In addition, patients with respiratory failure had significantly higher median levels of C-reactive protein (40.6 vs. 10.0 mg/l, P < 0.0001), median fibrinogen levels (4.3 vs. 3.4 g/l, P < 0.0001) and median D-dimer levels (0.3 vs. 0.2 mg/l, P = 0.0004)." (PMID 33468282, 2021). "The cases of PPCs (atelectasis, pulmonary infection, respiratory failure), CRP (C-reaction protein) and inflammatory cells (white cell count and percentage of neutrophils) and blood gas analysis at 12 h after operation, length of ICU and postoperative stay were recorded for each patient." (PMID 30567490, 2018). "In our study, NLR values were assessed in patients with chronic respiratory failure who were using domiciliary NIMV to investigate whether NLR is as valuable as CRP and procalcitonin for the suspicion of infection and assessment of treatment response." (PMID 30234089, 2018). "Moreover, DAH patients with MPA without acute respiratory failure often demonstrate significantly lower CRP levels than patients with acute respiratory failure." (PMID 28050304, 2016). "Age, sex, underlying disease, initial chest radiographic findings, initial CRP level, initial ANC, peak CK level, lowest lymphocyte count, worst chest radiographic findings, peak LDH level, and peak CRP level were the predictive factors for respiratory failure." (PMID 15200814, 2004). "Since both CRP and LDH are markers of inflammation, whether the initial LDH level is also an independent risk factor for death or respiratory failure needs further study." (PMID 15200814, 2004). "Inflammatory markers at patient admission (day 1) which correlated with increased respiratory failure through day 28 included: decreased lymphocytes and platelets, as well as increased D-dimer, white blood cell counts, blood glucose, urea, lactate, creatinine, procalcitonin, CRP, LDH, and troponin." (PMID 36716303, 2023). "Significant positive correlations were observed between inflammatory markers (CRP, IL-6) and both ICU admission and mechanical ventilation, underscoring the role of systemic inflammation in driving severe respiratory failure and critical care needs." (PMID 39857695, 2025). "At the same time, a minority of patients progress to a hyperinflammatory “cytokine storm” state with striking elevations of interleukin-6 (IL-6), C-reactive protein (CRP), ferritin, and D-dimer, which strongly correlate with respiratory failure and death." (PMID 41517263, 2025). "ROC analysis of variables associated with respiratory failure complicating MPP demonstrated that CRP, IL-10, APTT, D-dimer, and HB were statistically significant predictors of respiratory failure (P < 0.05)." (PMID 39849991, 2025). "The five strongest signals for elranatamab included increased c-reactive protein (N = 5, ROR = 10.29), uveitis (N = 4, ROR = 13.79), decreased red blood cell count (N = 4, ROR = 9.02), cellulitis (N = 3, ROR = 5.06) and respiratory failure (N = 3, ROR = 4.10)." (PMID 40880759, 2025). "In conclusion, higher Tei index, higher PRISM III score, higher CRP, an increased VIS in patients receiving CRRT, as well as respiratory failure at the time of CRRT commencement, were all related to higher mortality." (PMID 38133874, 2024). "Santa Cruz and colleagues established IL-6 as a biomarker for developing Fatal Severe Acute Respiratory Syndrome Coronavirus 2 (SARS-CoV-2) pneumonia due to its positive correlation with C-reactive protein (CRP) and respiratory failure." (PMID 39192275, 2024). "In multivariate logistic regression analysis, exosomal and serum miR-1258, NLR, NEU, CRP, WBC, PCT, sex, Respiratory failure and Cerebrovascular Disease were identified as independent predictors for AECOPD." (PMID 37884583, 2023).
respiratory failure (continued). "At the same time, if the patient develops respiratory failure, shock, CK ≥ 1000 U/L, CK-MB ≥ 100 U/L, SCr ≥ 100 mmol/L, BUN ≥ 7.5 mmol/L, or CRP ≥ 8 mg/L, close attention should also be given to changes in the patient's condition." (PMID 34906106, 2021). "It has been shown to reduce respiratory failure and in-hospital mortality rates, shorten hospital stays, and suppress postoperative CRP and cytokine elevations without increasing postoperative infectious complications." (PMID 40638018, 2025). "While CRP remains a valuable marker for inflammation, NLR and PLR provide additional layers of prognostic information, especially in predicting adverse outcomes such as ICU admission and respiratory failure." (PMID 40282925, 2025). "Furthermore, sST2 was the strongest parameter discriminating against the occurrence of acute respiratory failure and PESI scores >106 relative to C-reactive protein (CRP), creatinine, d-dimer, and serum lactate." (PMID 40672378, 2025). "Analysis of inflammatory markers and liver and kidney function tests in different groups of children with MPP revealed that those with respiratory failure had significantly elevated levels of white blood cells, neutrophil ratio, PCT, ESR, CRP, IL-6, IL-10, IFN-γ, ALT, AST, and LDH." (PMID 39849991, 2025). "Moreover, sST2 was the strongest parameter with a discriminative capacity for the development of acute respiratory failure and a PESI score >106 with respect to C reactive protein (CRP), creatinine, d-dimer, and serum lactate." (PMID 36902022, 2023). "He had an acute respiratory failure with the elevation of WBC count, CRP, and ESR." (PMID 35606506, 2022). "In the respiratory failure group, there was a significant difference in using immune checkpoint inhibitor (ICI) use within 90 days (p = 0.025) and the level of C-reactive protein (CRP) level (p = 0.017)." (PMID 36316726, 2022). "Eleven patients had a high CRP level or a history of ICI within 90 days as risk factors, whereas there were 7 patients who developed respiratory failure and 4 patients who did not develop respiratory failure." (PMID 36316726, 2022). "Laboratory values that can help diagnose these conditions are high levels of neutrophils, C-reactive protein (CRP), troponin, myoglobin, d-dimer, lactate dehydrogenase (LDH), and IL-6; these parameters and low lymphocyte counts predict progression to respiratory failure and death." (PMID 35172759, 2022). "Interestingly, a negative correlation was found between calprotectin and CRP in patients requiring mechanical ventilation, possibly reflecting the complex nature of the inflammatory response in severe respiratory failure." (PMID 41140665, 2025). "Notably, while adult studies associate NLR/CRP with CAP severity and neutrophil-mediated respiratory failure, our dataset lacked standardized CAP classifications and P/F measurements, hindering pediatric-adult mechanistic comparisons." (PMID 40464042, 2025). "Therefore, we think that the data from our investigation fit into this context: 41% of our investigated SSc patients developed an ES with the typical manifestations as non-infectious fever with elevated CRP levels, skin rash, pneumonitis with respiratory failure, and encephalopathy." (PMID 34539659, 2021). "Inflammatory markers (LDH, CRP, CPK, IL-6) were 2–20 times higher among patients with respiratory failure compared to patients without respiratory failure (p < 0.05)." (PMID 36105073, 2022). "Procalcitonin values were not well correlated with NLR, CRP, and PLT/MPV in patients with chronic respiratory failure." (PMID 30234089, 2018). "When differentiating an infection from chronic inflammation in patients with chronic respiratory failure NLR is easy, quick, and cheap to perform, CRP is moderately expensive, and not available in every center, and procalcitonin is expensive and also not available in every center." (PMID 30234089, 2018).
neutropenia (169 papers, 2007 to 2026). A decrease in the number of neutrophils found in the blood. "Among these markers, C-reactive protein (CRP) is the only biomarker present in the validated risk stratification algorithms mentioned by the 2017 International Pediatric Fever and Neutropenia Guidelines8." (PMID 37081067, 2023). "Many early indicators were associated with poor prognosis, while elevated CRP and neutropenia were the independent predictors for the 30-day mortality of children with laboratory-confirmed AB bacteremia." (PMID 37775747, 2023). "Our patient had a significant increase in CRP (108 mg/L), and elevated CRP levels and extreme neutropenia are essentially associated with worse survival." (PMID 36310874, 2022). "We identified ANC < 3.03 × 103 /μL, T-Bil ≥ 0.6 mg/dL, CRP < 0.13 mg/dL as risk factors for Grade 3/4 neutropenia in standard GnP therapy (CTCAE ver5.0)." (PMID 34260659, 2021). "Our findings indicate that low ANC, high T-Bil, and low CRP are risk factors for severe neutropenia in patients receiving GnP therapy, even if the clinical laboratory test values lie within the normal reference ranges." (PMID 34260659, 2021). "Multiple logistic regression analysis was performed to evaluate associations between neutropenia and relevant factors such as sex, age at onset, C-reactive protein level, nasopharyngeal microbiota profile, and GRSS." (PMID 33671944, 2021). "Multivariate analysis identified low absolute neutrophil count (ANC), high total bilirubin (T-Bil), and low C-reactive protein (CRP) as risk factors for Grade 3/4 neutropenia." (PMID 34260659, 2021). "C-reactive protein concentrations increased dramatically by week two, in association with neutropenia and infection." (PMID 32599718, 2020). "Duration of neutropenia, C-reactive protein level, and Multinational Association for Supportive Care in Cancer risk index were significant factors for 30-day mortality." (PMID 31179231, 2019). "Moreover, elevated CRP (more than 59.02 mg/L) and neutropenia were the independent risk factors for 30-day mortality." (PMID 37775747, 2023). "Previous studies in adults and children have proposed previous exposure to carbapenems, hospitalization time of ICU, invasive procedures performed, severity of the disease, red blood cell distribution width, C-Reactive Protein (CRP) and neutropenia were risk factors for the mortality of AB-BSI." (PMID 37775747, 2023). "Low ANC, high T-Bil, and low CRP may be risk factors for Grade 3/4 neutropenia in patients receiving GnP therapy, even if these laboratory values are within normal reference ranges." (PMID 34260659, 2021). "Procalcitonin (PCT) may be better than C-reactive protein (CRP) in helping identify patients with severe infection as the cause of temperature in neutropenia." (PMID 28056911, 2017). "In conclusion this study demonstrated that colonization with HA E. faecium 30 days prior to blood culture, combination of neutropenia and abdominal focus, age > 58 years, hospital stay prior to blood culture > 14 days and CRP level >125 mg/L are independent risk factors for E. faecium BSI." (PMID 24025668, 2013). "Blood tests at this point were unremarkable except for neutropenia, with a C-reactive protein (CRP) of < 1 mg/L." (PMID 39916608, 2025). "Initially, blood tests showed mild neutropenia and an elevated C-reactive protein (CRP) of 100 mg/L." (PMID 41404449, 2025). "We conducted chi-square tests using the variables extracted as risk factors for neutropenia (age, RBC, PLT, Neutr, and ALP) and factors affecting delayed recovery (CRP level and range of neutrophil count decline from days 1 to 8)." (PMID 39991570, 2025). "They determined that 18F-FDG-PET-CT in the context of increased CRP was capable of detecting infection in situations of severe neutropenia." (PMID 38399711, 2024).